KRAS (KRas proto-oncogene, GTPase)
Diseases named in the same sentence as KRAS in open-access papers (continued):
Sharing a sentence is not in itself a finding about the gene and the disease.
cancer (continued). "We found that PI3K-AKT signaling pathway was significantly inhibited in NRAS, KRAS, and HRAS mutant-cancer cell lines upon treatment with BAY 11-7082 as observed by reduced p-AKT protein level." (PMID 38982514, 2024). "In summary, our study shows that KRASG12C inhibitors induce the formation of primary cilia and activate Hh signaling, which is responsible for re-expression of KRAS and reacquired resistance against KRASG12C inhibitors in cancer cells." (PMID 38225225, 2024). "Given the role of oncogenic KRAS in driving immune suppression, prevention of MAPK reactivation is crucial to block cancer cell-intrinsic adaptive resistance and the maintenance of an immunosuppressive TME and the potential for cross-resistance." (PMID 39322643, 2024). "Cancer vaccine ELI-002 2P enhances lymph node delivery and immune response using amphiphile (Amph) modification of G12D and G12R mutant KRAS (mKRAS) peptides (Amph-Peptides-2P) together with CpG oligonucleotide adjuvant (Amph-CpG-7909)." (PMID 38195752, 2024). "Downstream of active KRAS, hyperactivation of the small GTPase RAC1 drives proliferation and cytoskeletal remodelling in PDAC and other cancers." (PMID 38712822, 2024). "However, no immunotherapies targeted KRAS mutation have been approved for clinical treatment although some bispecific antibodies targeting mutant RAS neoantigens have shown the ability to treat cancer in mouse models." (PMID 38752985, 2024). "GSEA analysis showed that PDIA3 and its related differential genes are involved in a variety of important biological functions closely related to cancer and affect OSCC through the Hedgehog, TGF-β, Wnt-β catenin, and KRAS signaling pathways." (PMID 38213579, 2023). "A previous study (in the GSE39582 cohort) classified CRC into four subtypes according to dominant molecular and respective biological characteristics: “CIN”, “dMMR”, “KRASm” (for KRAS-mutant) and “CSC” (for cancer stem cells)." (PMID 37488178, 2023). "Here discussed are that KRAS, MYC, and ARF6 are biochemically and functionally closely related with each other in promoting cancer malignancy and immune evasion." (PMID 37158894, 2023). "Co-targeting of ribosomal proteins along with the target-specific inhibitors (here KRAS G12C-mutant inhibitor) will pave way for the development of precision treatment, such as using CRISPR-Cas and T-cell immunotherapy, in cancer." (PMID 37396909, 2023). "However, this notion still may not fully explain why KRAS mutations are so much more common in PDAC than in other types of cancer." (PMID 37158894, 2023). "Some anti-cancer drugs have been developed and applied in clinical cancer therapies by targeting genes such as EGFR, KRAS, etc.." (PMID 36833194, 2023). "Signaling pathways, including mTOR, KRAS, STAT, and other integrin/receptor-mediated pathways like NOTCH, WNT, TGF-beta, and hedgehog signaling, play crucial roles in cancer progression." (PMID 37958444, 2023). "Our results showed that SJ-C1044 impaired the growth of all KRAS and BRAF mutant cancer cells, with IC50 values ranging from 160 to 628 nM." (PMID 37504287, 2023).
cancer (continued). "In KRAS-mutant CRC cells, combination treatment with β-elemene and cetuximab enhanced the cytotoxic effect against cancer cells by inducing ferroptosis and inhibiting EMT." (PMID 37346068, 2023). "KRAS is a member of the RAS family and is currently one of the most thoroughly researched targets for cancer treatment due to its prevalence in avariety of deadly malignancies." (PMID 37822837, 2023). "In one study, cancer driver genes ARID1A, PIK3CA, KRAS, and PPP2R1A were identified in 21% of endometriotic lesions." (PMID 37573406, 2023). "Among these potential druggable alterations, EGFR, KRAS, and PIK3CA gene alterations were the most common, while CDK pathway (CDK4/6, CDKN2A/2B), FGFR1/2/3, BRAF, RET was uncommon across pan-cancer." (PMID 36910668, 2023). "However, such inhibitors have had limited or no impact on cancers bearing KRAS mutations." (PMID 37210549, 2023). "The activation of KRAS triggers downstream proteins such as MEK, RAF, PI3K, AKT and mTOR proteins, to induce transcription, endocytosis, migration and metastasis of cancer cells." (PMID 37686543, 2023). "A non-covalent inhibitor that binds preferentially to the inactive state of KRAS while sparing NRAS and HRAS is reported, indicating that most KRAS oncoproteins cycle between an active state and an inactive state in cancer cells." (PMID 37258666, 2023). "KRAS mediates the downstream PI3K/AKT and RAF/ERK signaling pathways to promote cancer cell proliferation and metastasis." (PMID 37937641, 2023). "For a great example, mutant KRAS and mutant EGFR were found in EVs and transferred to recipient cells leading to cancer progression." (PMID 36671802, 2023). "Alteration of common oncogenic proteins, such as epidermal growth factor receptor (EGFR), KRAS, BRAF, and c-Myc, drives tumorigenesis across 38 cancer types." (PMID 36694209, 2023). "As SHP2 depletion activated TGFβ signalling in a number of cancer cell lines, we sought to understand the effect of SHP2 inhibition in a KRAS mutant background." (PMID 38102334, 2023). "AKT control of PD-L1 traffic was similar in non-transformed and transformed cells and it was unaffected by whether the driver oncogene was mutant EGFR or KRAS, indicating this is a fundamental feature of PD-L1 biology and not specific to cancer cells or specific driver mutation." (PMID 36915197, 2023). "Although monotherapy with MEK inhibitors has shown limited clinical efficacy in patients with KRAS-mutant tumors, in other types of RAS mutant cancer patients, MEK inhibitors alone have exhibited considerable antitumor activity." (PMID 38001714, 2023). "GSEA enrichment analysis showed that OGN was mainly enriched in cancer-related signaling pathways such as EMT and KRAS." (PMID 37352032, 2023). "Cancer progression is related to the upregulation of anti-apoptotic proteins such as PLK1 (Polo-like kinase 1), KRAS, and cell growth factor." (PMID 37514088, 2023). "It is well-established that aberrant activation of mutant KRAS can override oncogene-induced senescence (OIS), thereby promoting the survival and proliferation of cancer cells." (PMID 37872156, 2023). "The GSEA analysis results of BIRC3 observed that various cancer-promoting pathways were enriched in the high expression group including IL2 STAT5 signaling, IL6-JAK-STAT3 signaling, KRAS signaling, PI3K-AKT-MTOR signaling and TNFA signaling via NFKB." (PMID 38130918, 2023). "Gain/loss-of-function assays, cell viability assay, xenograft models, and IHC staining were conducted to evaluate the anti-cancer effects of co-inhibition of ST8SIA6-AS1/PLK1 pathway and KRAS both in vitro and in vivo." (PMID 38104151, 2023). "While VCP has been heavily studied in the context of other cancer types, the mechanisms of VCP that modulate KRAS-mutant PDAC growth remain less well understood." (PMID 36923647, 2023).
cancer (continued). "Drug library screening of 294 FDA-approved or clinical trial-tested compounds in KRAS-independent and -dependent cancer cell lines identified AT7519, a CDK 1, 2, 7, and 9 inhibitor as a potent inhibitor of the viability of KRAS-dependent cells." (PMID 37209817, 2023). "This review will provide insights into KRAS dependency in PDAC and analyze recent data on inhibitors of KRAS signaling, focusing on how cancer cells establish compensatory escape mechanisms." (PMID 37298264, 2023). "Low-abundance SNV fractions of KRAS G12D, EGFR L858R, and EGFR T790M cancer markers were detected in under 2 h, and the results were validated by comparing the data with those obtained using ddPCR." (PMID 36979592, 2023). "To understand how Setd2 deficiency increases chromatin accessibility to induce the expression of KRAS signature, we first focused on Etv1, one of the transcription factors downstream of ERK signaling and a well-defined oncogene in multiple cancer types." (PMID 36810256, 2023). "The selective cytotoxicity observed in KRAS-mutant and BRAF-mutant cancer cells further supports the potential therapeutic utility of SJ-C1044 in targeting specific oncogenic mutations." (PMID 37504287, 2023). "Patients with KRAS-mutant NSCLC can benefit from immunotherapy, and clinical trials evaluating the efficacy of adoptive cell therapy and cancer vaccines are ongoing." (PMID 37662925, 2023). "We also found that other known cancer-related genes were also altered at low frequency including APC (n = 5), KRAS (n = 2), SETD2 (n = 2), DAXX (n = 1) and STAG2 (n = 1)." (PMID 37524847, 2023). "Thus, two features of KRAS, the G4 structure in the mRNA and the rare codons in the gene, will prevent the excessive expression of its protein product, and hence its mutations may be favored over mutations in other RAS genes in certain types of cancers." (PMID 37158894, 2023). "Here I discussed the mutually inseparable relationships and cooperation of KRAS, MYC, and ARF6 in cancer malignancy and immune evasion." (PMID 37158894, 2023). "In this review, we explore KRAS-dependency in PDAC and analyze recent data on KRAS signaling inhibitors, focusing on how cancer cells establish compensatory escape mechanisms." (PMID 37298264, 2023). "The inhibition or activation of ULK1 is often effective in overcoming cancer drug resistance to tyrosine kinase inhibitors (TKI), selective BRAF inhibitors, 5-fluorouracil (5-FU), KRAS drugs, doxorubicin, tamoxifen, and crizotinib." (PMID 36671802, 2023). "Then, oncogenic mutant KRAS augments inflammation and launches an immunosuppressive TME that subsequently plays a pivotal role in cancer progression." (PMID 37444617, 2023). "Growing evidence shows that KRAS-mutation-driven cancer cells, including CRC, exhibit the metabolic vulnerability of being addicted to glutamine (Gln), indicating that targeting Gln metabolism may be a promising therapeutic strategy for KRAS-mutation-driven cancers." (PMID 37937641, 2023).
cancer (continued). "EGFR and KRAS, the types of oncogenic drivers in NSCLC, can activate the PI3K/AKT/mTOR pathway, which enhances cancer cell proliferation, metabolism, and survival." (PMID 37568193, 2023). "One of the key pathways regulated by KRAS is the PI3K/Akt/mTOR pathway, which plays a critical role in lipid metabolism and is frequently dysregulated in cancer." (PMID 38020549, 2023). "RAS was one of the earliest identified human oncogenes and RAS family genes, KRAS (KRAS4A and KRAS4B), NRAS, or HRAS, the most commonly dysregulated proto-oncogenes in human cancer." (PMID 36175301, 2023). "Dual inhibition of STAT3 and KRAS, achieved by nano-antibody SBT-100, would be an ideal treatment for this type of cancer to overcome ADR in ovarian and many other types of cancer." (PMID 36902166, 2023). "Similar to the NAT group of carcinomas, we found a statistically significant correlation between CAIX expression and the KRAS status when biopsy CAIX values were considered (biopsy p < 0.0454; surgical specimens p < 0.0921)." (PMID 36768903, 2023). "G-quadruplexes, G4, have been found in telomeric DNA, as well as in the promoter regions of a number of genes, including cancer oncogenes, such as MYC and KRAS." (PMID 35328482, 2022). "We next tested the antiproliferative effects of TH-Z835 in other non-G12D mutant cancer cell lines, including 4T1 (KRAS(WT)), MIA PaCa-2 (KRAS(G12C)), CFPAC-1 (KRAS(G12V)), and HCT116 (KRAS(G13D)) cells." (PMID 35075146, 2022). "Cancer is heterogeneous in space and time, and recurrent tumors may not have KRAS mutations." (PMID 35312176, 2022). "Among the downstream targets of KRAS, the Hippo pathway with YAP and TAZ (YAP/TAZ) is crucial for cancer initiation and progression." (PMID 35326559, 2022). "Finally, ranking cancer driver mutations by their correlation with glutamine reveals that KRAS and ERBB4 have the strongest negative correlation (indicating that mutation is associated with a reduction of glutamine), and PRCC, JUN and PIK3CA mutations rank highly with an accumulation of glutamine." (PMID 36321551, 2022). "Thus, we speculate that a fine interplay between TERT and KRAS signaling is critical to drive proper tissue renewal, and that balanced activation of those two is critical to avoid deleterious consequences such as cancer initiation." (PMID 35149726, 2022). "In parallel to our studies with mutant KRAS, we set out to identify a role for AGO2 in mutant HRAS and NRAS-driven cancers." (PMID 35923912, 2022). "Among the included processes, NF-κB signaling, KRAS signaling, and the complement response were highly correlated with NET score in most cancer types." (PMID 35432310, 2022). "Regarding the capability of KRAS and BRAF mutant tumors to create an immunosuppressive microenvironment by interfering with the cancer-immunity cycle, various studies have shown that MEKi can restore an immune stimulatory and anti-tumorigenic microenvironment." (PMID 35965494, 2022). "The NRAS gene and its family KRAS and HRAS have been explained to be related to different types of cancers." (PMID 36430761, 2022). "Oncoproteins that commonly mutate or genetically alter in cancer cells, including the oncogenic KRAS, oncogenic BRAF, and activated PI3K/AKT, have been shown to result in glucose metabolic reprogramming in cancer cells." (PMID 35163079, 2022).
cancer (continued). "The KRAS oncogene is the major oncogenic driver of PDAC (86 – 91%), and is considered a master oncogenic regulator that drives cancer hallmarks including sustained proliferative signaling and evading growth suppression." (PMID 36531078, 2022). "Like the KRAS gene, BRAF is also part of the Ras family that targets the RAS/RAF/MEK/ERK pathway; together, they both account for 7-25% and 5-20% of all cancers as well as 30-45% and 8–10% of CRC for both KRAS and BRAF, respectively." (PMID 35782059, 2022). "According to our findings, NMNGs in pan-cancer were significantly correlated with a number of signaling pathways, including TNFA signaling via NFKB, KRAS signaling, interferon-gamma response, inflammatory response, and epithelial-mesenchymal transition (EMT)." (PMID 36726460, 2022). "Oncogenic KRAS drives downstream activation of RAF/MEK/ERK and PI3K/AKT signaling, which promotes survival, invasion, and migration of cancer cells." (PMID 35203351, 2022). "With ADAP1’s ability to tune the KRAS–ERK–AP-1 pathway, which is involved in several pathologies including cancer, an ADAP1-specific compound would be worth exploring beyond HIV-1 latency reversal." (PMID 35232997, 2022). "Among most of the descendant cancer cells, more cancer-related changes were obtained, such as in CCNE1, POU2AF1, and KRAS." (PMID 35951662, 2022). "There are three ras genes related to human cancer: HRAS, KRAS, and NRAS, which are located on chromosomes 11, 12, and 1, respectively." (PMID 35680848, 2022). "This review intends to elucidate the mechanisms of resistance to immunotherapy in KRAS-driven NSCLC and highlight the TME functions altered by immunoinhibitors, immunostimulators, and cancer metabolism." (PMID 35582540, 2022). "Therefore, a combination therapy involving XPO1 and KRAS G12C inhibitors can be a viable option, especially considering that preclinical and clinical studies have already reported the emergence of resistant subpopulations of cancer cells in response to KRAS G12C inhibitor monotherapy." (PMID 35573474, 2022). "The researchers detected the activation of KRAS in the production of epithelial-mesenchymal transition (EMT) and cancer stem cell-like cells (CSC)." (PMID 35444235, 2022). "Among newly identified genes, eleven other cancer targets were detected: MPL; ERBB4; VHL; FGFR3; KIT; KDR; PTEN; KRAS; PTPN11; ERBB2; and SMARCB1." (PMID 35621644, 2022). "Thus, careful cytometric statistics may be required for early KRAS+ cancers." (PMID 36201559, 2022). "While some cancers acquire amplification or overexpression of PHGDH, the first and rate-limiting step in this pathway, other types of cancers activate oncogenes such as MYC, MDM2, KRAS, and NRF2, leading to increased SSP enzyme expression." (PMID 35316216, 2022). "AGO2’s RISC activity and miRNA duplex unwinding were inhibited by interaction with mutant KRAS, suggesting that the RAS–AGO2 interaction plays a dynamic role in promoting mutant KRAS-driven cancer." (PMID 35923912, 2022). "Our previous work identified a novel interaction between KRAS and AGO2 in both WT and mutant KRAS cell lines across multiple cell lineages and cancers via coimmunoprecipitation (Co-IP) followed by mass spectrometry (co-IP MS)." (PMID 35923912, 2022).